PCK2 (phosphoenolpyruvate carboxykinase 2, mitochondrial)
Diseases named in the same sentence as PCK2 in open-access papers (continued):
Sharing a sentence is not in itself a finding about the gene and the disease.
breast carcinoma (16 papers, 2020 to 2025). "To explore the underlying roles of PCK2 in breast cancer cell proliferation, we assessed the effect of PCK2 on cell cycle progression using flow cytometric analysis." (PMID 35757841, 2023). "In addition, hypoxia-inducible factor 1-α (HIF1-α) in breast cancer negatively regulates PCK2 at the transcriptional level causing breast cancer tumor-repopulating cells (TRCs) to grow in anoxic environments." (PMID 33142842, 2020). "Because mTORC1 is an important regulator of protein synthesis, cell growth and metabolism in response to amino acids and growth factors, we evaluated whether PCK2 affects the metabolism of ER+ breast cancer cells and investigated its association with mTORC1 signaling." (PMID 35757841, 2023). "The roles of hypoxia-reprogrammed TCA cycles in promoting human breast cancer cell growth via a HIF-1α-mediated PCK2 pathway have been reported." (PMID 38729966, 2024). "Third, we demonstrated that PCK2 affects mTORC1 activation upon nutritional stress in ER+ breast cancer." (PMID 35757841, 2023). "PCK2 is also involved in the regulation of mTORC1 pathway activation by nutrition status in ER+ breast cancer cells." (PMID 35757841, 2023). "Because higher expression of PEPCK‐M was found in ER+ breast cancer samples than in ER− breast cancer samples and ER+ breast cancer is the most common subtype, we evaluated the function of PCK2 in ER+ breast cancer." (PMID 35757841, 2023). "The results suggest that PCK2 promotes the proliferation of ER+ breast cancer cells via activation of the mTORC1 pathway, as it does in other cancer types." (PMID 35757841, 2023). "In this study, we showed that PCK2 promotes the proliferation of ER+ breast cancer cells via upregulation of the mTORC1 and RB/E2F1 axes, which affects cell cycle progression." (PMID 35757841, 2023). "PCK2 is also involved in the regulation of mTORC1 pathway activation by nutrient status in ER+ breast cancer cells." (PMID 35757841, 2023). "Because the mRNA expression of PCK2 was increased in breast cancer according to TCGA analysis, immunohistochemical staining for PEPCK‐M was performed to determine the expression pattern of PEPCK‐M in breast cancer." (PMID 35757841, 2023). "Taken together, the results clarify that PCK2 promotes cell cycle progression by regulating mTORC1 activation and the responses of ER+ breast cancer cells to glutamine and glucose supplementation." (PMID 35757841, 2023). "PCK2 increased the ECAR and OCR in ER+ breast cancer cells, suggesting that PCK2 regulates glycolysis and mitochondrial oxidative phosphorylation in ER+ breast cancer cells." (PMID 35757841, 2023). "Decreased cell proliferation and G0/G1 arrest were induced in ER+ breast cancer cell lines by knockdown of PCK2." (PMID 35757841, 2023). "We knocked down or overexpressed PCK2 in breast cancer cell lines to investigate the function of PEPCK‐M in breast cancer." (PMID 35757841, 2023). "Consistent with a role in cancer metabolism and in entosis, PCK2 is overexpressed in breast carcinoma." (PMID 36002449, 2022). "PCK2 has a tumor suppressing effect in melanoma and liver cancer, and has a pro-cancer effect in lung and breast cancer." (PMID 32699530, 2020). "In breast cancer cells, hypoxia reduced the expression of PCK2, suggesting a possible interaction of gluconeogenesis and hypoxia." (PMID 32777161, 2020). "Additionally, several cancer cells, such as non-small cell lung carcinoma and breast cancer, express high levels of PCK2, which controls mitochondrial PEP synthesis and tumor cell growth under low-glucose conditions 82–86." (PMID 41446167, 2025). "PCK2 also regulates nutrient status‐dependent mTORC1 pathway activation in ER+ breast cancer." (PMID 35757841, 2023). "In addition, glucose uptake, intracellular glutamine levels, and mTORC1 pathways activation by glucose and glutamine in ER+ breast cancer were attenuated by PCK2 knockdown." (PMID 35757841, 2023).
breast carcinoma (continued). "The gene-gene interactions of deregulated glucose related genes in breast cancer, and it was found that deregulated glucose related genes show high interactions with PFKFB2, PFKFB4, FBP2, PCK2, ADH5 and other genes involved in glucose metabolism." (PMID 38173442, 2024). "We also found that PCK2 promoted cell cycle progression, particularly the G1/S transition, and induced upregulation of E2F1, cyclin D1, cyclin D2, and CDK4 in ER+ breast cancer cells." (PMID 35757841, 2023). "Although overexpression of PCK2 was found in breast cancer, the expression status of PEPCK‐M and the role of PCK2 in different subtypes of breast cancer are not well understood." (PMID 35757841, 2023). "Second, we demonstrated that PCK2 regulates the mTORC1 and RB/E2F1 axes and promotes cell proliferation and cell cycle progression in ER+ breast cancer." (PMID 35757841, 2023). "PCK2 plays an anti-cancer role in HCC and melanoma, while PCK2 also plays a carcinogenic role in both lung and breast cancer." (PMID 32210020, 2020). "Therefore, PCK2 promotes cell proliferation and cell cycle progression by regulating mTORC1 and E2F1 in ER+ breast cancer." (PMID 35757841, 2023). "In our current study, PCK2 promoted mTORC1 pathway activation but did not affect the sensitivity of ER+ breast cancer cells to an mTOR inhibitor (data not shown)." (PMID 35757841, 2023). "PCK2 regulates drug resistance and the metabolism in pNET cells was not the same as that in ER+ breast cancer cells, suggesting a differential function of PCK2 by cancer type." (PMID 35757841, 2023). "We knocked down PCK2 by using a lentiviral approach in the ER+ breast cancer cell lines MCF‐7 and T47D and established stable clones of these cell lines with and without knockdown of PCK2." (PMID 35757841, 2023).
colon carcinoma (12 papers, 2014 to 2025). "Elevated expression of PCK2 has been observed in several cancer types, including colon cancer, non-small cell lung cancer (NSCLC) and hepatocellular carcinoma (HCC)." (PMID 40182032, 2025). "A dual PCK1 and PCK2 inhibitor that was efficient in reducing subcutaneous colon cancer growth in vivo was recently found to be well-tolerated without inducing weight loss, albeit slightly reducing basal glucose levels in starved mice." (PMID 33540663, 2021). "Briefly, we showed that the lncRNA FEZF1-AS1 was up-regulated in colon cancer tissues and functioned as oncogene by interacting with PCK2 to regulate cellular metabolism." (PMID 37304670, 2021). "All these results showed that FEZF1-AS1 deficiency potentially affected the homeostasis of energy metabolism in cell, which impeded the proliferation of colon cancer cells, and this effect was partially dependent on PCK2." (PMID 37304670, 2021). "PCK2 overexpression in FEZF1-AS1 knockout cells partially rescued the tumor inhibitory effect on colon cancer cells both in vitro and in vivo." (PMID 37304670, 2021). "Knockout and rescue experiments indicated that FEZF1-AS1 inhibited colon cancer cell proliferation, invasion, and migration, partially dependent on PCK2, by disturbing the homeostasis of energy metabolism of the mitochondria." (PMID 37304670, 2021). "In colon cancer, the mitochondrial isoform of PCK2 has lower expression and our findings suggested that targeting ATGL recovers PCK2 levels." (PMID 34845203, 2021). "Because relative gene expression of PCK2 was only present in less than 3% of colon cancers according to TCGA database, their study focused on PEPCK-C." (PMID 29262588, 2017). "A colon carcinoma model, SW480 was selected instead of HeLa because it carries only one copy of chromosome 14 where the PCK2 gene is located, as compared to the multiple copies found in the HeLa genome, simplifying CRISPR/Cas9 use." (PMID 33413684, 2021). "These DEGs, significantly altered in human colon cancer tissue (TCGA) (Supplemental S4), are ones with both emerging roles (SEC24D, ABCC3, ATGL2B, and PCK2) and established roles (MYC and MUC2) in colonic tumorigenesis." (PMID 34845203, 2021). "As expected, intermediates in glycolysis like D-Glucose 6-phosphate and Lactate decreased significantly in KO cells and could not be rescued by PCK2 overexpression, suggesting that other proteins interacted with FEZF1-AS1 to regulate the utilization of glucose in colon cancer cells." (PMID 37304670, 2021).
Hyperinsulinemia (12 papers, 2011 to 2024). An increased concentration of insulin in the blood. "Many upregulated genes related to glucose metabolism were upregulated by hyperinsulinemia, such as G6pc3, Hk1, Pck2 and Aldoa, some of which were reverted to baseline by starvation." (PMID 34921686, 2022).
steatosis (11 papers, 2015 to 2025). Increased lipid within the cytoplasm of cells. "Although these animals showed normal glucose production from pyruvate, changes in the expression of important genes for glucose metabolism, such as GCK, G6Pase, PCK2, and GLUT2, suggest that as a result of steatosis, glycolysis could be impaired." (PMID 28101297, 2016).
melanoma (10 papers, 2017 to 2025). A malignant, usually aggressive tumor composed of atypical, neoplastic melanocytes. "In patients with melanoma or clear cell renal cell carcinoma, the PCK2 expression was also lower in metastatic tumor than in primary tumor." (PMID 38720107, 2024). "Our western blot analysis confirmed increased expression of CYP27A1, which was upregulated in the bile acid metabolic pathway, and three additional glycolytic genes (PKM2, PHGDH, and PCK2) in melanoma CD8+ TILs compared to PBMCs." (PMID 38023136, 2023). "In contrast to the tumor-promoting effects of PCK1 in melanoma, PCK2 downregulation has been indicated as a metabolic characteristic of TRCs from melanoma." (PMID 37250903, 2023). "Other regulatory factors, such as ATF4, or HIF, bind to the promoter of PCK2 to enhance its transcription in breast and cervix carcinomas or melanoma, respectively." (PMID 37304670, 2021). "In melanoma, PCK2 down-regulation accelerates the biosynthesis and transport of citric acid from mitochondria to the cytoplasm." (PMID 32699530, 2020). "Opposite to those findings in melanoma, we found that PCK2 was upregulated in more aggressive prostate tumors and elevated PCK2 levels enriched TICs." (PMID 29137367, 2017). "Conversely, other studies have shown that PCK2 overexpression could suppress the cancer progression in renal cell carcinoma and melanoma." (PMID 40182032, 2025). "A recent study also found that PCK2 can regulate TICs in melanoma cells." (PMID 29137367, 2017). "However, PCK2 has been found to be downregulated in TICs in melanoma cells and repressed their tumorigenic ability." (PMID 29137367, 2017). "However, recently, several studies had suggested that PCK2 overexpression could suppress the progression of renal cell carcinoma and melanoma." (PMID 39193344, 2024). "Notably, PCK2 downregulation acts as a metabolic feature of TRCs from melanoma, which may bring novel therapeutic targets for the treatment of melanoma." (PMID 37250903, 2023). "PCK2 overexpression could impair TRC growth and block tumor progression of melanoma." (PMID 37250903, 2023).
non-small cell lung carcinoma (9 papers, 2016 to 2025). A group of at least three distinct histological types of lung cancer, including non-small cell squamous cell carcinoma, adenocarcinoma, and large cell carcinoma. "Non-small-cell lung cancer cells (NSCLC) with PCK2 depletion show decreased levels of pyruvate and citrate from glutamine." (PMID 37304670, 2021). "PCK2 expression was reported to be elevated in non-small-cell lung carcinoma (NSCLC) and is regulated by glucose and required for in vivo tumour growth." (PMID 28378759, 2017). "Targeting PCK2 could be used as a potential therapeutic strategy for the treatment of non-small-cell lung cancer." (PMID 39193344, 2024).
prostate carcinoma (9 papers, 2017 to 2024). A carcinoma that arises from epithelial cells of the prostate gland. "Prostate cancer patient database information revealed that higher levels of PCK2 expression were associated with more aggressive tumors and lower survival rates." (PMID 29137367, 2017). "Finally, using patient databases, we found that higher PCK2 expressions are associated with more aggressive tumors and lower survival rates in prostate cancer patients." (PMID 29137367, 2017). "We demonstrate that SOX4 promotes NE trans-differentiation by activating the SOX4/PCK2 pathway to induce carbohydrate metabolism reprogramming in prostate cancer." (PMID 39014441, 2024). "Accordingly, tumor‐initiating cells (TICs) from prostate cancer showed higher PCK2 levels than the parental cells and PCK2 silencing reduced TIC numbers by affecting levels of reactive oxygen species and protein acetylation." (PMID 32777161, 2020). "Our metabolic characterization of PCK2 knockdown in prostate cancer cells found that knocking down PCK2 resulted in acetyl-CoA accumulation, increased protein acetylation, and dramatically reduced the proportion of TICs." (PMID 29137367, 2017). "Information from prostate cancer patient databases revealed that higher PCK2 levels correlated with more aggressive tumors and lower survival rates." (PMID 29137367, 2017). "Our data suggest that by shunting anion OAA as PEP from mitochondria to the cytosol PCK2 regulates tumor initiation of prostate cancer cells through reducing the TCA cycle, ROS level, and production of citrate and acetyl-CoA." (PMID 29137367, 2017). "We determined that elevated levels of phosphoenolpyruvate carboxykinase isoform 2 (PCK2) are critical for the metabolic switch and the maintenance of TICs in prostate cancer." (PMID 29137367, 2017). "In prostate cancer patients, high PCK2 is detected in more aggressive tumors, and patients with high PCK2 expression have lower survival rates." (PMID 29137367, 2017). "Together, these results indicate that modulation of cellular acetyl CoA level and protein acetylation is an important factor in PCK2's ability to maintain TICs in prostate cancer cells." (PMID 29137367, 2017). "Our data suggest PCK2 regulates tumor initiation of prostate cancer cells by reducing the mitochondrial tricarboxylic acid (TCA) cycle activity and thereby production of citrate and acetyl-CoA." (PMID 29137367, 2017). "Here we show that elevated levels of phosphoenolpyruvate carboxykinase isoform 2 (PCK2) are critical for the metabolic switch and maintenance of TICs in prostate cancer." (PMID 29137367, 2017). "Further, PCK2 (cytosolic and mitochondrial isoforms), which is involved in the citric acid cycle (TCA), have increased expression associated with enhanced growth of lung and prostate cancer." (PMID 34845203, 2021). "High PCK2 expression predicted a worse overall survival in prostate cancer." (PMID 32777161, 2020). "Using published prostate cancer microarray datasets, we found a much higher PCK2 expression in metastatic prostate cancer samples compared to normal tissue or primary cancer tissue in two datasets (GDS1439 and GDS2524), indicating that PCK2 is highly expressed in aggressive prostate cancer." (PMID 29137367, 2017). "To analyze whether PCK2 regulates the TIC characteristics of prostate cancer cells, we determined the number of TICs in PCK2-knockdown clones using flow cytometry." (PMID 29137367, 2017). "First, we found that selected TIC-enriched prostate cancer cell clones use more glucose and secrete more lactate than their TIC-low counterparts.Second,we determined that PCK2 is critical for the metabolic switch that generates and maintains TICs in prostate cancer." (PMID 29137367, 2017). "We next examined the PCK2 expression in clinical prostate cancer samples." (PMID 29137367, 2017). "Since knocking down PCK2 reduced TICs in prostate cancer cells, we then asked whether this is related to cellular acetylation change." (PMID 29137367, 2017).
prostate carcinoma (continued). "Notably, we found that knocking down PCK2 could significantly reduce the proportion of TICs in prostate cancer cells, indicating that PCK2 is a potential target for therapies against TICs." (PMID 29137367, 2017). "Prostate cancer from metastatic patients showed higher PCK2 expression levels than prostate cancer tissue from nonmetastatic patients." (PMID 32777161, 2020).
colorectal cancer (8 papers, 2017 to 2024). A primary or metastatic malignant neoplasm that affects the colon or rectum. "Discussion: These findings suggest that transcriptional control of PCK2 is one mechanism used by PGC-1β and ERRα to promote glutamine metabolism and colorectal cancer cell survival." (PMID 36230802, 2022).
liver cancer (6 papers, 2015 to 2024). An epithelial or non-epithelial malignant neoplasm that arises from the liver. "All in all, PCK2 knockdown promoted the biological functions of liver cancer cell proliferation,invasion and migration." (PMID 38890507, 2024). "Yet, little is known about PCK2 in liver cancer and immune invasion and checkpoint." (PMID 38890507, 2024). "Experiments showed that overexpression of PCK2 could inhibit the proliferation, migration and invasion ability of liver cancer cells." (PMID 38890507, 2024). "In addition, as demonstrated by the wound-healing assays and transwell assays, PCK2 knockdown also promotes the ability of liver cancer cells to migrate and invade." (PMID 38890507, 2024). "Therefore, exploring the expression, survival prognosis, mutation, functional enrichment, metastasis, immune invasion, immune checkpoint, and proliferation migration and invasion of PCK2 in liver cancer will lay a foundation for further understanding of its mechanism." (PMID 38890507, 2024). "PCK2 and its related genes are mainly enriched in the growth, invasion, metastasis, EMT, PPAR, WNT, PI3K/AKT and other biological signaling pathways of liver cancer cells, which opens a new window for the treatment strategy of liver cancer." (PMID 38890507, 2024). "The decreased expression of PCK2 may promote EMT by activating cytokines, a series of signaling pathways and altering immune infiltration, and ultimately lead to tumor immune evasion, low survival rate and increased invasivity in patients with liver cancer." (PMID 38890507, 2024). "However, the PCK2 gene has been less studied in LIHC, so we collected a total of 455 samples from the GSE112790 and GSE102079 datasets, including 29 normal tissues and 426 liver cancer tissues." (PMID 38890507, 2024).
cervical carcinoma (5 papers, 2020 to 2024). A carcinoma arising from either the exocervical squamous epithelium or the endocervical glandular epithelium. "PCK2 participates in the supportive adaptations of breast and cervical cancer cells to adapt to the stress state in the tumor environment." (PMID 33142842, 2020). "A gene ontology enrichment analysis of co-expressed genes in all available datasets of cervical cancer (SEEK at seek.princeton.edu) was then devised to expose PCK2 co-expressed pathways." (PMID 33413684, 2021).
renal cell carcinoma (5 papers, 2020 to 2025). "One of these, PCK2, has been reported as a tumor suppressor in renal cell carcinoma." (PMID 36358633, 2022). "In order to clarify the changes of PCK2 methylation level in RCC, we performed Bisulfite Sequencing PCR (BSP) on 5 pairs of renal cell carcinoma tissues and adjacent tissues." (PMID 33052225, 2020).